VWF (von Willebrand factor)
Diseases named in the same sentence as VWF in open-access papers (continued):
Sharing a sentence is not in itself a finding about the gene and the disease.
Sepsis (continued). "We previously reported that elevation in endothelial biomarkers ANGPT2/ANGPT1 ratio, VCAM1, and vWF distinguished children with ARDS due to indirect (e.g., extrapulmonary sepsis or trauma, shock, transfusion, pancreatitis) compared to direct (e.g., pneumonia, aspiration, drowning) lung injury." (PMID 35913450, 2022). "Moreover, the effects of FTB on the levels of coagulation-related factors vWF, TM, P-selectin, PAI-1, PAF, and TAT in rats with sepsis were assessed." (PMID 36408247, 2022). "Recent studies have suggested a reciprocal correlation between VWF and ADAMTS13 in sepsis." (PMID 33606732, 2021). "There are some studies showing a role of VWF and ADAMTS13 in pulmonary diseases, sepsis and cancer." (PMID 34134634, 2021). "Compared with classical blood biomarkers of systemic inflammation (e.g., CRP), the proteins detected in this study, including haptoglobin, vWF, MBL1, MRC1, sCD14, and LBP, showed a very early response to infection, indicating their potential in serving as new early markers of infection or sepsis." (PMID 31803186, 2019). "Their findings suggested that the ADAMTS-13 levels, as well as the vWF/ADAMTS-13 ratio, combined with the clinical SIRS criteria could provide a valuable tool for sepsis mortality prediction." (PMID 31434239, 2019). "In contrast, others have demonstrated that VWF parameters are reciprocally correlated with ADAMTS-13 activity in severe sepsis and septic shock without prognostic value regarding the outcome." (PMID 28775254, 2017). "In a prospective study of 45 ICU patients with sepsis, patients with nonpulmonary sepsis had higher levels of plasma vWF, with good predictive and prognostic values for ARDS." (PMID 26980924, 2016). "Several endothelium-related molecules such as angiopoietins, vWF and sICAM-1 were demonstrated to be correlated with severity of sepsis, and similarly, HSPA12B, mainly located in endothelial cells, was considered as a predictor for prognosis of severe sepsis." (PMID 24977412, 2014). "Although not measured in our study, plasma vWF activity is known to be increased in patients with sepsis, and to correlate with mortality." (PMID 20482750, 2010). "Like other markers of endothelial cell activation, vWF has not been compared with measures of endothelial NO bioavailability in sepsis." (PMID 20482750, 2010). "Moreover, it has been shown that RBC transfusion increases the circulating levels of von Willebrand factor, indicating endothelial activation independent of sepsis or organ injury." (PMID 41246019, 2025). "In one recent study, the authors reported that plasma vWF antigen levels were elevated in patients with sepsis (730 ± 384%) (p ≤ 0.0001) relative to patients without sepsis (463 ± 460%, p ≤ 0.05) and healthy controls (100 ± 65%) based on a study of 40 patients with sepsis and 40 patients without it." (PMID 39200994, 2024). "Notably, the combination of cilengitide and ISE produced comparable outcomes in mitigating vWF-mediated endothelial permeability disruption, underscoring the protective role of ISE against endothelial hyperpermeability during sepsis by suppressing the vWF–integrin αvβ3 interaction." (PMID 38921594, 2024). "Finally, vWF, an endothelial product that mediates platelet adhesion at sites of vascular damage, has been reported to be higher in patients with sepsis than those without." (PMID 33477776, 2021). "Therefore, lower plasma vWF levels in blood type O could affect the NET activity, possibly affecting coagulation and the immune response related to sepsis." (PMID 33076323, 2020). "Further clinical studies are needed to clarify if restoration of normal activity levels of ADAMTS13 (i.e., with plasma or recombinant ADAMTS13 infusions) may neutralize VWF-system prevalence and prevent microvascular occlusion and organ failure in patients with SIRS and sepsis." (PMID 28634421, 2017).
Sepsis (continued). "Notably, within the PPI network analysis, key proteins including ICAM1, Resistin, TIMP1, VWF, CRP, and HMGB1 were identified at the central nodes of the network module, revealing a significant difference (P < 0.05) between the normal group and the sepsis group." (PMID 38951753, 2024). "At day 1, the vWF/ADAMTS13 ratio was significantly elevated in both patients with and without sepsis in the ICU relative to the healthy controls." (PMID 39200994, 2024). "The lack of correlation between the plasma vWF or vWF/ADAMTS13 ratio and IntelliSep results suggests that these two markers probably measure different pathways of activation for sepsis (endothelial activation vs. neutrophil/monocyte activation)." (PMID 39200994, 2024). "Indeed, elevated plasma levels of vWF had a sensitivity of 87% and a specificity of 77% for the prediction of ARDS development in the setting of nonpulmonary sepsis." (PMID 26980924, 2016).
myocardial infarction (80 papers, 2008 to 2025). Gross necrosis of the myocardium, as a result of interruption of the blood supply to the area, as in coronary thrombosis. "The aim of this study was to use arterial endothelial molecular imaging to mechanistically evaluate endothelial-associated VWF as a therapeutic target for reducing remote plaque activation after myocardial infarction (MI)." (PMID 38693516, 2024). "It is considered that elevated plasma PAI-1 concentrations alongside fibrinolysis suppression and findings of increased plasma levels of FVIII, vWF, fibrinogen, t-PA, and D-dimer lead to an additional risk of the occurrence of myocardial infarction." (PMID 38541980, 2024). "Reduced plasma ADAMTS13 and increased plasma VWF are also risk factors for the development of arterial and inflammatory diseases, including myocardial infarction and ischemic stroke." (PMID 33946285, 2021). "In contrast to the increased risk of bleeding, individuals with the highest levels of vWF have been shown to have an ∼2× increased risk of thrombotic events, such as thromboembolic stroke or acute myocardial infarction." (PMID 31768485, 2019). "ABO polymorphism increases the susceptibility to myocardial infarction through some pathways, such as increasing vWF level, soluble intercellular adhesion molecule-1 level, soluble P-selectin level, and soluble E-selectin level." (PMID 28811939, 2017). "Elevated levels of VWF during thrombolysis in acute myocardial infarction (AMI) patients have been associated with poor recanalization and worse outcomes." (PMID 29410644, 2017). "Increased β2-GPI/VWF ratio correlated with a two to three fold reduced risk of myocardial infarction in elderly men." (PMID 25297919, 2015). "Clinical studies have indeed demonstrated that reduced ADAMTS-13 activity and increased VWF levels are risk factors for the development of myocardial infarction and ischemic stroke." (PMID 25297919, 2015). "Additionally, an imbalance of ADAMTS-13 activity and vWF plasma concentration are risk factors for the development of myocardial infarction, ischemic stroke, pre-eclampsia, malignant (or cerebral) malaria and antiphospholipid syndrome." (PMID 33920144, 2021). "This increase in VWF secretion might result in higher concentrations of VWF in plasma, which in fact is also associated with an increased risk of myocardial infarction, ischemic stroke, and arterial thrombosis." (PMID 30972039, 2019). "Moreover, acute coronary syndrome (ACS), acute myocardial infarction, stroke and ischemic events have been associated with increased levels of plasma VWF in several population-based studies." (PMID 31620451, 2019). "Plasma factor VIII (FVIII) and von Willebrand factor (VWF) levels have been associated with the rate and severity of arterial thrombus formation and have been linked to outcomes following thrombolytic therapy in acute myocardial infarction patients." (PMID 29410644, 2017). "A study on mice showed the influence of ADAMTS-13 and vWF deficiency on a myocardial infarction (MI), induced by the ligation of the left anterior descending coronary artery." (PMID 33096906, 2020). "Unfolded Von Willebrand Factor (VWF) is increased in thrombotic pathologies such as myocardial infarction." (PMID 39726607, 2024). "Higher levels of VWF were also reported in cyanotic patients with Eisenmenger syndrome and in adult patients with previous myocardial infarction." (PMID 38399555, 2024). "Many lines of evidence suggest that VWF is not only a marker, but also a truly important effector in the pathogenesis of myocardial infarction." (PMID 36984822, 2023). "The purpose of the study was to assess the validity of plasma VWF antigen (VWF: Ag) levels as a predictor of clinical outcomes after acute myocardial infarction (AMI)." (PMID 36684571, 2022). "Ex vivo studies demonstrated that ARC1779 is a potent and specific inhibitor of vWF, even for acute myocardial infarction patients (AMI) who have an elevated vWF activity." (PMID 33918821, 2021).
myocardial infarction (continued). "In the general population, increased VWF and decreased ADAMTS13 have been associated with myocardial infarction and ischemic stroke, probably by inducing a prothrombotic tendency." (PMID 34134634, 2021). "Various lines of evidence indicate that VWF is not only a marker but also actually an important effector in the pathogenesis of myocardial infarction." (PMID 30972039, 2019). "ARC15015 is the second generation, chemically modified, anti-VWF aptamer that was designed to target shear-dependent platelet aggregation in the clinical setting of myocardial infarction." (PMID 31620451, 2019). "Previous studies have shown a variation in plasma level of von Willebrand factor (vWF) in acute myocardial infarction (AMI) patients but with contentious results." (PMID 29163836, 2017). "vWF is an acute phase reactant and therefore high plasma levels are seen in several acute illnesses, including acute myocardial infarction (AMI) and ischemic stroke." (PMID 28570705, 2017). "For example, patients with Thrombolysis in Myocardial Infarction (TIMI) grade 3 were reported to have less vWF in plasma than that of other patients." (PMID 29163836, 2017). "The physiological relevance of β2-GPI as a regulator of VWF activity became apparent in a study involving a large cohort of aged men with myocardial infarction." (PMID 25297919, 2015). "HRP detected by PFA-100 in acute myocardial infarction is reversible by DD of aspirin and clopidogrel; the response is predicted by basal levels of VWF and ADAMTS-13." (PMID 24453831, 2013). "In fact, increased vWF levels predict adverse cardiac events and recurrence of myocardial infarction in patients with acute coronary syndromes." (PMID 21619612, 2011). "It has therefore been suggested that circulating levels of ADAMTS-13 may influence circulating levels of VWF and/or its function, and it may therefore influence risk of thrombotic events such as myocardial infarction (MI) in the general population." (PMID 18194418, 2008). "Odds ratios (95% confidence intervals) for risk of myocardial infarction for ADAMTS-13 and von Willebrand factor (VWF), adjusted for three sets of risk factors (I-III), with and without adjustment (+/−Adj)." (PMID 18194418, 2008). "Results and Conclusion: The results show that peptides from the plasma of patients with myocardial infarction promote endothelial cells to release both von Willebrand factor and endothelin-1, increasing vasoconstriction and shifting hemostatic balance toward a prothrombotic state." (PMID 36837440, 2023). "For example, the rise in vWF is likely to be greater following acute myocardial infarction than the rise observed in our study, and it is unlikely that the magnitude of change in sP-selectin is equivalent to the 4-fold rise observed in disseminated intravascular coagulation." (PMID 35250627, 2022). "Patients with previous myocardial infarction, for instance, have higher VWF concentrations." (PMID 36684571, 2022). "The epicatechin-induced decrease in GpIb-positive microparticles could impair their reactivity to thrombin and von Willebrand factor, and might have a direct impact on myocardial infarction pathogenesis." (PMID 32992756, 2020). "vWF plays a key role in preventing and treating life-threatening heart attacks and strokes." (PMID 31768485, 2019). "In addition, VWF concentrations appear to increase and function as a cofactor in vasoocclusive diseases such as myocardial infarction or cerebrovascular disease." (PMID 30026593, 2018). "Moreover, reduced activity of ADAMTS13 toward VWF has been suggested to promote both ischemic stroke and myocardial infarction." (PMID 29326937, 2017). "Hence, we investigated the number of capillary vessels at 12 weeks after myocardial infarction by using an antibody to vWF, a well-known marker of the mature microvasculature." (PMID 27226084, 2016).
myocardial infarction (continued). "A GWAS study found that ABO locus showed the top signal for myocardial infarction in patients with angiographic coronary artery disease (CAD), and concluded that the variation linked to group O and reduced vWF, was protective against myocardial infarction in CAD patients." (PMID 25592833, 2015). "Prior medical research in cardiology demonstrated that elevated VWF in combination with decreased ADAMTS13 levels is associated with endothelial damage and the development of heart disease, including heart failure, atrial fibrillation, and myocardial infarction." (PMID 40725629, 2025). "Third, the absence of longitudinal follow-up data restricts our ability to assess the prognostic value of the vWF and FVIII levels over time, such as their impact on clinical outcomes like myocardial infarction, revascularization, or mortality." (PMID 41007843, 2025). "One study reported that MSCs pretreated with Ang-2 improved the therapeutic efficacy of myocardial infarction through enhancing paracrine regulation (higher production of VEGF and von Willebrand factor) and angiogenesis." (PMID 36064450, 2022). "A recent study showed that transplantation of peripheral blood-derived early EPCs was positive for endothelial markers such as CD31, VEGFR-2, von Willebrand factor, and CD105 in patients with acute myocardial infarction." (PMID 34445558, 2021). "In the ENTIRE-TIMI 23 sub-study, the reduced success of thrombolysis (estimated by the thrombolysis in myocardial infarction (TIMI) flow grade and the corrected TIMI frame count) positively correlated with the plasma levels of VWF." (PMID 33096906, 2020). "The efficacy of AJvW-2 on shear-specific inhibition of VWF-GPIbα interaction was tested in ACS patients (12 with unstable angina, 20 with acute myocardial infarction) with enhanced Shear-Induced Platelet Aggregation (SIPA)." (PMID 31620451, 2019). "In the British Regional Heart Study (BRHS), we have assayed a range of coagulation markers in men aged 60–79 years, and have previously reported associations of fibrinogen, VWF, Factors VIII and IX, and D-dimer with incident myocardial infarction (MI) and CHD death." (PMID 28043678, 2017). "High circulating VWF: Ag concentrations have been linked to the no-reflow phenomenon and increased microvascular resistance, which could hinder successful reperfusion despite large-vessel recanalization, not only in patients with ischemic stroke but also with acute myocardial infarction." (PMID 40217918, 2025). "Increased levels of VWF and reduced levels of ADAMTS13 activity may contribute to the pathogenesis of acute myocardial infarction and might prove to be important mediators of AMI progression." (PMID 32095288, 2020). "Our data suggest that increased levels of VWF and reduced levels of ADAMTS13 activity may contribute to the pathogenesis of acute myocardial infarction." (PMID 32095288, 2020). "The research findings showed that BMSC-EVs increased the survival rate of cardiomyocytes, increased the expression of vWF and VEGF, and activated the Akt/Nrf2/HO-1 pathway, resulting in overall improvements in outcomes for myocardial infarction (MI)." (PMID 38915448, 2024). "In a prior publication, we showed that CECs (CD138|von Willebrand Factor positive, CD45 negative) in PB samples were morphologically distinct from the surrounding WBCs, and CEC count was significantly higher in myocardial infarction patients than that of the healthy control." (PMID 35159025, 2022).